APOL1 (apolipoprotein L1)
Description:
May play a role in lipid exchange and transport throughout the body. May participate in reverse cholesterol transport from peripheral cells to the liver. A component of trypanosome lytic factor of human serum; plays a crucial role in killing Trypanosoma brucei by forming pores in parasite lysosomal membranes and sensitizing T.brucei to oxidation-stimulated osmotic lysis.
Synonyms: Apo-L; ApoL; ApoL-I; FSGS4
Tractability: Small molecule: a high-quality ligand is known. Antibody: its Gene Ontology location is reachable by antibodies, with high confidence; UniProt places it where antibodies can reach, with medium confidence; UniProt predicts a signal peptide or a membrane-spanning region. PROTAC: ubiquitination databases record sites on it; its protein half-life has been measured; a small molecule that binds it is known.
Gene: Protein-coding gene on chromosome 22 (36,253,071 to 36,267,530, forward strand). Ensembl gene ENSG00000100342.
Subcellular location: Secreted
Pathways (Reactome):
Metabolism of proteins: Post-translational protein phosphorylation; Regulation of Insulin-like Growth Factor (IGF) transport and uptake by Insulin-like Growth Factor Binding Proteins (IGFBPs)
Vesicle-mediated transport: Scavenging of heme from plasma
Gene Ontology:
Molecular function: chloride channel activity; lipid binding; protein binding
Biological process: antibacterial innate immune response; chloride transmembrane transport; innate immune response; lipid transport; lipoprotein metabolic process
Cellular component: blood microparticle; extracellular region; high-density lipoprotein particle; very-low-density lipoprotein particle; endoplasmic reticulum lumen; membrane
Genetic constraint (gnomAD): Loss-of-function variants: 19 observed, 16.4 expected, observed/expected ratio (o/e) 1.16, 90% interval 0.81 to 1.68. The upper end of that interval is the gene's LOEUF score, 1.68, which puts it in group 6 of 6, group 1 being the genes least tolerant of losing a copy. Missense variants: 523 observed, 504.78 expected, observed/expected ratio (o/e) 1.04, 90% interval 0.96 to 1.11. Synonymous variants: 195 observed, 193.75 expected, observed/expected ratio (o/e) 1.01, 90% interval 0.89 to 1.13.
Gene-disease validity (ClinGen):
ClinGen rates the evidence that APOL1 causes each of these diseases.
focal segmental glomerulosclerosis 4, susceptibility to (autosomal recessive): Definitive.
Homologues: Orthologues: rat Apol3l1 (33% identical), rat LOC120093819 (32% identical), mouse Apol10b (29% identical), mouse Apol9b (29% identical), mouse Apol11a (28% identical), mouse Apol9a (28% identical), rat Apol9a (27% identical), mouse Apol11b (24% identical), mouse Apol10a (22% identical), zebrafish apol (18% identical), Caenorhabditis elegans F07F6.8 (10% identical), Caenorhabditis elegans F07F6.7 (9% identical). Paralogues in human: APOL2 (52% identical), APOL3 (40% identical), APOL4 (36% identical), APOL6 (25% identical), APOL5 (23% identical), APOLD1 (12% identical).
Diseases named in the same sentence as APOL1 in open-access papers:
APOL1 is named in the same sentence as 195 diseases in open-access papers, as found by Europe PMC text mining. Sharing a sentence is not in itself a finding about the gene and the disease. The quoted sentences say what the papers report.
chronic kidney disease (135 papers, 2011 to 2026). Impairment of the renal function secondary to chronic kidney damage persisting for three or more months. "The 7 other positive tests included amyloidosis (TTR, N = 3), Alport syndrome (COL4A3, N = 2), polycystic kidney disease (PKD1, N = 1), and susceptibility to end stage renal disease (APOL1, N = 1)." (PMID 40126616, 2025). "Carriers of two apolipoprotein L1 gene risk variants (RVs), termed G1 and G2, are at increased risk for chronic kidney disease." (PMID 41043427, 2025). "The potential risk of post-donation chronic kidney disease (CKD)/end stage kidney disease (ESKD) was discussed in detail with the donor especially in the context of her high risk APOL1 genotype." (PMID 40821938, 2025). "Their risk to develop HIVAN or another chronic kidney disease is strongly associated with two apolipoprotein L1 (APOL1) risk alleles (APOL1-RA), G1 and G2." (PMID 40747773, 2025). "The primary focus of APOL1 research has been on kidney diseases, particularly its association with focal segmental glomerulosclerosis and chronic kidney disease." (PMID 38254861, 2024). "Significantly, the presence of the APOL1 risk alleles G1 and G2, which are associated with increased susceptibility to podocyte injury, has been implicated in the accelerated progression of chronic kidney disease (CKD)." (PMID 38542298, 2024). "For example, in AA patients, end-stage renal disease is linked to the presence of the APOL1 nephropathy risk genotype, which is more common in the AA general population." (PMID 39624492, 2024). "The common coding variant APOL3 p.Q58* is a genetic modifier of chronic kidney disease risk in individuals monoallelic for APOL1 G1/G2 carrier status in individuals of African ancestry." (PMID 39163132, 2024). "In Africans carrying a high frequency of APOL1 alleles, the prevalence of chronic kidney disease (CKD) is up to 16%." (PMID 35327595, 2022). "Two alleles in the Apolipoprotein L1 (APOL1) gene were associated with chronic kidney disease; these alleles are common in individuals of African ancestry but rare in European descendants." (PMID 36588788, 2022). "As renalase expression is associated with chronic kidney disease, the interesting possibility that APOL1 interacts with this pathway requires further investigation." (PMID 36250097, 2022). "Variants of the APOL1 gene are associated with chronic kidney disease (CKD) in people of African ancestry, although evidence for their impact in people with HIV are sparse." (PMID 35497797, 2022). "Genetic variants in apolipoprotein L1 (APOL1), a protein that protects humans from infection with African trypanosomes, explain a substantial proportion of the excess risk of chronic kidney disease affecting individuals with sub-Saharan ancestry." (PMID 36279295, 2022). "Two variants at the APOL1 gene, encoding apolipoprotein L1, account for more than 70% of the increased risk for chronic kidney disease in individuals of African ancestry." (PMID 35072009, 2022). "More recently, associations between variants in apolipoprotein L1 (APOL1) and chronic kidney disease in AAs have been established, and there is some evidence these variants play a role in increased CVD risk." (PMID 34733899, 2021). "The APOL1 variants thereby restore trypanosomal killing but do so at the cost of increased risk for chronic kidney disease." (PMID 34765626, 2021). "Two recently evolved human APOL1 variants (renal-risk variants) are associated with increased risk of chronic kidney diseases." (PMID 34252458, 2021). "The APOL1 risk alleles G1 and G2 increase the risk of chronic kidney disease and are associated with an elevated risk of developing hypertension-associated end stage renal disease, FSGS, Lupus-nephritis, and HIVAN." (PMID 35095882, 2021). "Human APOL1 variants G1 and G2 protect against human-infective trypanosomes but also confer a higher risk of developing chronic kidney disease." (PMID 34331942, 2021).
chronic kidney disease (continued). "Of the six human APOL genes, APOL1 is the most studied; the APOL1 protein is known for its ability to kill some Trypanosomatids and for its association with chronic kidney disease in humans." (PMID 34252458, 2021). "We have recently learned how air pollution increases the risk of chronic kidney disease in carriers of the APOL1 high-risk genotype." (PMID 32984227, 2020). "APOL1 alleles G1 and G2 are associated with faster progression to lupus nephritis (LN)-associated end-stage renal disease (LN-ESRD) in African Americans." (PMID 31664093, 2019). "This study shows that 37% of the Afro-descendant patients with chronic kidney disease had an APOL1 high-risk allele." (PMID 31929905, 2019). "African polymorphisms in the gene for Apolipoprotein L1 (APOL1) confer a survival advantage against lethal trypanosomiasis but also an increased risk for several chronic kidney diseases (CKD) including HIV-associated nephropathy (HIVAN)." (PMID 31661509, 2019). "C-terminal mutations in APOL1 are associated with a constellation of complex diseases of the kidney, including chronic kidney disease (CKD), HIV-associated nephropathy (HIVAN), and focal segmental glomerulosclerosis (FSGS)." (PMID 31158233, 2019). "The frequency of APOL1 risk variants tends to be high in Ghana and Nigeria21 and our data show a lower prevalence of chronic kidney disease in Ghana and Burkina Faso with a higher prevalence in South Africa, where APOL1 risk variants are less common." (PMID 31708144, 2019). "The prevalence of mutations of the APOL1 gene among Afro-descendant patients with chronic kidney disease for the G1 and the G2 variants can be of 20–22% and 13–15%, respectively." (PMID 31929905, 2019). "APOL1 risk alleles associate with chronic kidney disease in African Americans, but the mechanisms remain to be fully understood." (PMID 30417125, 2018). "Two coding sequence variants (G1 and G2) of Apolipoprotein L1 (APOL1) gene have been implicated as a higher risk factor for chronic kidney diseases (CKD) in African Americans when compared with European Americans." (PMID 29967295, 2018). "APOL1 polymorphisms have been best characterized by their associations with human chronic kidney disease (CKD); individuals carrying two RA copies in any combination (G1/G1, G1/G2, G2/G2) are considered at high risk." (PMID 28850570, 2017). "We report that the association of APOL1 chronic kidney disease variants with HAT susceptibility are markedly different for the two subspecies." (PMID 28537557, 2017). "A 2010 study demonstrated the existence of two independent sequence variants of the APOL1 gene in African-Americans and association of these variants with hypertension-attributed end-stage renal disease (ESRD) and focal segmental glomerulosclerosis (FSGS)." (PMID 28842513, 2017). "A heterozygous advantage model has been proposed for APOL1 G1 and G2 in which recessive susceptibility to chronic kidney disease is balanced by dominant resistance to one or both forms of human African trypanosomiasis." (PMID 28537557, 2017). "Two independent groups discovered an association between chronic kidney disease and the two coding variants G1 and G2 in the APOL1 gene." (PMID 27138898, 2016). "Genetic variants of APOL1 are described to be associated with the development of end stage renal diseases in African Americans." (PMID 27138898, 2016). "An association has been reported between APOL1 G1/G2 with chronic kidney disease in SCD, possibly through an increased risk of hemoglobinuria." (PMID 27669006, 2016). "Several studies have confirmed that the APOL1 variants are important risk factors for the development of focal segmental glomerulosclerosis and other forms of chronic kidney disease in African Americans and Hispanics." (PMID 27138898, 2016).
chronic kidney disease (continued). "A recent study also demonstrated that the risk of progression of chronic kidney disease is approximately two times higher in African-Americans with APOL1 variants despite adequate blood pressure control." (PMID 27148508, 2016). "For example, patients with two APOL1 renal risk alleles are prone to develop hypertension and chronic kidney disease complicated by FSGS." (PMID 26156092, 2015). "We also found association with eGFR for a deletion in APOL1 originally associated with end-stage renal disease." (PMID 23028791, 2012). "APOL1 G1 and G2 risk alleles are associated with an increased risk of chronic kidney disease." (PMID 41497611, 2025). "However, hypertensive nephropathy is more common in patients of African origin who carry the APOL1 gene variant, and this can increase the risk of hypertension-related end-stage renal disease by ~ 8 – 10 times." (PMID 40115864, 2025). "In order to examine associations between APOL1 genotype and hospitalisation from any infectious disease, we performed an additional logistic regression using age, sex, Townsend deprivation index, chronic kidney disease, and principal components 1–4 as covariates." (PMID 38360481, 2024). "For example, the APOL1 gene variants, which are more common in African American populations, have been linked to an increased risk of chronic kidney disease (CKD) and could potentially modify the severity of ADPKD." (PMID 39457385, 2024). "Each phenotype was tested for an association with APOL1 genotype using logistic regression with age, sex, Townsend deprivation index, evidence of chronic kidney disease (eGFR < 60 mL/min/1.73 m2 or uACR > 3 mg/mmol or algorithmically-defined ESKD), and principal components 1–4 used as covariates." (PMID 38360481, 2024). "The APOL1 variants predominantly affect podocytes, key cells in the kidney glomerulus, leading to compromised glomerular filtration barrier integrity, proteinuria, and eventual end-stage renal disease (ESRD)." (PMID 38542298, 2024). "Two coding alleles within the APOL1 gene, G1 and G2, found almost exclusively in individuals genetically similar to West African populations, contribute substantially to the pathogenesis of chronic kidney disease (CKD)." (PMID 39163132, 2024). "Therefore, this mouse model is a suitable model to study cardiovascular disease with human APOL1 variant, uncomplicated by effects of chronic kidney disease." (PMID 39803526, 2024). "In addition, the APOL1 variants that confer protection against trypanosomiasis are associated with chronic kidney disease, particularly in the context of virus-induced inflammation such as COVID-19." (PMID 36880831, 2023). "Two ethnicity-specific genes have been associated with end-stage renal disease of unknown etiology in other populations: apolipoprotein L1 (APOL1) gene in African Americans, and Glutathione S-transferase Mu 1 (GSTM1) null phenotype in the Mexican population." (PMID 36674063, 2023). "For example, in Hispanic/Latino individuals, Native American single nucleotide variants (SNVs) at the SLC16A11 gene are associated with risk of diabetes, and African ancestry SNVs in the APOL1 gene (related to plasmodium pathogen resistance) are associated with chronic kidney disease." (PMID 37461045, 2023). "We also replicated other previously reported African population-specific associations, such as ACKR1 for neutropenia and reduced white blood count levels and a missense variant, rs73885319 in APOL1 with kidney-related conditions such as end-stage renal disease." (PMID 37425708, 2023). "and the data presented herein, we suggest that inhibition of exon 4 splicing may serve as a potential therapeutic target to mitigate the risk of chronic kidney disease mediated by APOL1 mutants." (PMID 35072009, 2022). "For chronic kidney disease, this knowledge could help establish public health strategies for monitoring patients and understanding the impact of the Apolipoprotein L1 genetic variants in admixed populations." (PMID 36588788, 2022).
chronic kidney disease (continued). "However, high-risk APOL1 status has been associated with the progression of kidney function to ESKD among those with chronic kidney disease." (PMID 36250097, 2022). "Two risk variants in the APOL1 gene on chromosome 22, collectively referred to as APOL1 nephropathy risk alleles are associated with an increased risk of chronic kidney disease, and kidney failure (end-stage kidney disease, ESKD) among self-reported African-American (AA) individuals." (PMID 36250097, 2022). "However, in an example of heterozygote advantage, the cost of protection from two copies of the variant APOL1 genes is an increased lifetime risk of developing chronic kidney disease." (PMID 34331942, 2021). "However, two ApoL1 coding variants are associated with a highly increased risk of chronic kidney disease." (PMID 34316015, 2021). "This has led to the hypothesis that a sustained increase in RRV expression is a cause of APOL1-driven chronic kidney disease." (PMID 32427098, 2020). "SuPAR acts as a tripartite complex of suPAR, APOL1 risk variants, and αvβ3 integrin on podocytes, resulting in podocyte foot process effacement, disrupted glomerular barrier function, proteinuria, and thereby chronic kidney disease." (PMID 31061709, 2019). "The association between APOL1 chronic kidney disease risk variants and human African trypanosomiasis reveals a more complex picture of selection and human evolution than was originally hypothesized." (PMID 28537557, 2017). "For example, among African-Americans, the risk variants in APOL1 are associated with a more than 10-fold increase in risk of focal segmental glomerulosclerosis and high-risk carriers have a twofold greater risk of progression to end-stage renal disease." (PMID 27148508, 2016). "While studies in adult AA populations demonstrated strong recessive association of APOL1 G1 and G2 genetic variants with glomerular and vascular disease progression, there is limited information on its role in children with chronic kidney disease (CKD), particularly for cardiovascular comorbidities." (PMID 27900314, 2016). "Third, while the phenotype of APOL1-associated glomerulosclerosis is usually described according to the incidence of end-stage renal disease (ESRD), for which G1 and G2 behave as recessive alleles as described in the introduction, there are other ways to classify the glomerulosclerosis phenotype." (PMID 23300552, 2012). "We also tested two markers in APOL1 previously associated with end-stage renal disease." (PMID 23028791, 2012). "People of African ancestry are at substantially increased risk of chronic kidney disease (CKD), and this has partially been attributed to genetic variants of the apolipoprotein L1 (APOL1) gene." (PMID 39448372, 2025). "Apolipoprotein L1 (APOL1) high-risk variants are major determinants of chronic kidney disease (CKD) in people of African ancestry." (PMID 39448372, 2025). "Genetic variants in the protein-coding regions of APOL1 are associated with an increased risk and progression of chronic kidney disease (CKD) in African Americans." (PMID 38542298, 2024). "Polymorphisms in APOL1 are a risk factor for chronic kidney disease (CKD), including human immunodeficiency virus (HIV)-associated nephropathy and FSGS." (PMID 37509442, 2023). "People of Sub-Saharan African ancestry are at higher risk of developing chronic kidney disease (CKD), attributed to the Apolipoprotein L1 (APOL1) gene risk alleles (RA) G1 and G2." (PMID 37925499, 2023). "In several countries including Brazil, APOL1 mutations are considered as risk factors and determinants of chronic kidney disease (CKD)." (PMID 35308512, 2022). "Significant evidence links the presence of APOL1 high risk alleles to the excess prevalence of chronic kidney disease (CKD) in individuals of African ancestry." (PMID 34071920, 2021).